ADK (adenosine kinase)
Diseases named in the same sentence as ADK in open-access papers (continued):
Sharing a sentence is not in itself a finding about the gene and the disease.
cancer (31 papers, 1978 to 2025). A tumor composed of atypical neoplastic, often pleomorphic cells that invade other tissues. "Therefore, we believe that ADK targeting has more potential as a cancer treatment target once the causal manipulatory effects of ADK have been confirmed with future in vivo studies." (PMID 31921385, 2019). "Low ADK expression might be a risk factor and biomarker for cancer development." (PMID 37538114, 2023). "ADK downregulation was shown to suppress proliferation, viability, migration, and invasion of cancer cells." (PMID 39941076, 2025). "Inhibition of tumor cell proliferationand induction of apoptosis after ADK inhibitor treatment, particularly in thecolorectal cancer cell line HT-29, have been described in a series ofexperimental papers." (PMID 37538807, 2023). "CCAT1::CASC8 was only recently reported in the fusion catalog generated by DEEPEST fusion, and VCL::ADK was only previously reported in a study of cancer cell lines." (PMID 37323575, 2023). "This review article focuses on recent updates on ADK and its two isoforms, and its actions in adenosine receptor-independent pathways, including methylation modification and epigenetic changes in cancer pathology." (PMID 35721189, 2022). "Targeting enzymes in the TME that decrease the levels of adenosine (such as ADA and ADK) can significantly prevent the activation of adenosine receptors and enhance cancer immunotherapy." (PMID 35327609, 2022). "In summary, additional studies are needed to fully understand the role of adenosine in cancer pathology and to reveal the anticancer potential of ADK inhibition." (PMID 35721189, 2022). "Several other genes residing at the association loci reported include known drug targets with repurposing opportunities, such as GRK6, CD44, SLC38A10, and ADK, with potential implications across multiple different cancers and auto-inflammatory diseases." (PMID 31937769, 2020). "These functions of ADK isoforms strongly support a differential role for ADK-L versus ADK-S in cancer." (PMID 31921385, 2019). "The present study, for the first time, provides experimental evidence to mechanistically dissect the differential roles of two ADK isoforms in cancer pathology." (PMID 31921385, 2019). "In particular, the increase in S201A activity directs a new approach to regulate ADK activity and explore its biological role related to ADK dysfunction, disease, and cancer." (PMID 31370143, 2019). "Koyama and Tsuji demonstrated that MZB is metabolized into an active form, MZB 5′-P, by adenosine kinase (AK) in carcinoma cells." (PMID 20052390, 2009). "ADK can influence immune systems and aid in the development of cancer." (PMID 37999212, 2023). "Thus, transcriptomic signatures commonly altered by LJ4827 and5ITU treatment in cancer cells were examined to identify an anticancerMoA other than AdK." (PMID 37396870, 2023). "In addition to nervous system disorders, the changes in the level of ADK enzyme attract researchers who study diabetes, vascular inflammation, and cancer." (PMID 35327609, 2022). "The general increase of purine metabolizing enzymes including ADK may allow accelerated purine metabolism to support the growth of cancer." (PMID 35721189, 2022). "Conversely, accumulating evidence supports ADK as a therapeutic target in cancer." (PMID 35721189, 2022). "Together, selective inhibition of ADK-L is indicated as a novel adenosine receptor-independent strategy to offer a new perspective on cancer therapy, which may achieve more precise cancer intervention than general ADK or ADK-S manipulation." (PMID 35721189, 2022). "We should always bear in mind the challenge that increased adenosine levels can: 1) inhibit immune and inflammatory responses; 2) stimulate angiogenesis: epigenetic regulation of pro-angiogenic genes by ADK, and is thought to be another mechanism by which ADK is involved in cancer." (PMID 35721189, 2022). "The mechanism of purine derivatives in cancer cells is very complex and mainly depends on ADK." (PMID 34204594, 2021).
cancer (continued). "It was shown that the use of an ADK inhibitor completely inhibited KR-induced apoptosis and cytotoxicity, which suggests that cancer cell selectivity may be achieved based on the known overexpression of ADK by cancer cells." (PMID 32955614, 2020). "ADK plays a significant role in affecting apoptosis and may become a target for the treatment of cancer." (PMID 31156704, 2019). "Interest in ADK has increased regarding its role in modulating the adenosinergic pathway in cancer." (PMID 31921385, 2019). "We thus demonstrated that 2-oxo-Ado causes growth arrest and apoptosis dependent on ADK, AK2 and the formation of 2-oxo-ATP (triphosphate form) similarly to various modified adenosines, such as 8-Cl-Ado and 2-Cl-Ado, which are potent anti-cancer drugs." (PMID 28747712, 2017). "In addition, the changes in ADK levels might explain the beneficial effects of metformin on cancer, age-related diseases and inflammatory diseases which should be further investigated in the future." (PMID 39060559, 2024). "Use of an ADK inhibitor has been shown to inhibit kinetin riboside-induced apoptosis and cytotoxicity, which suggests that cancer-cell selectivity may be achieved based on ADK overexpression by cancer cells." (PMID 37538114, 2023). "Indeed, a newly proposed mechanism of isoform switching in dysfunctional cells was evidenced in a recent human cancer study from twelve solid cancer types, which may also apply to ADK isoforms on tumorigenesis." (PMID 31921385, 2019). "Further, while the effects of ADK-L might be unrelated to adenosine receptor function, ADK knockdown-mediated expression changes on proteins that are crucially involved in cancer pathology warrant further investigation for insights on potential mechanisms as a novel therapeutic target." (PMID 31921385, 2019). "Due to the observed different expression profiles of ADK-L and ADK-S, as well as their different molecular features and distinguished subcellular location, it is natural to suspect that the two ADK isoforms may act via different mechanisms in cell biology and cancer pathology." (PMID 31921385, 2019). "These efforts led to the identification of two additional tumors with ADK::KAT6B rearrangement and one carcinoma carrying RPS6KB1::VMP1 fusion." (PMID 40661875, 2025). "These 17 translocations were further analyzed in 1,059 mutation-negative NSCLCs, which resulted in the identification of two additional tumors with ADK::KAT6B rearrangement and one carcinoma carrying RPS6KB1::VMP1 fusion." (PMID 40661875, 2025). "Fusions with ADK, BRAF, and NTRK1 were reported repeatedly both in our cohort and in multiple cancer types." (PMID 32471990, 2020). "The abnormality of ADK and AMPD1 changes the metabolic homeostasis of cells and promotes the progression of cancer cells." (PMID 31156704, 2019). "ADK serves as a metabolic-epigenetic link—by controlling adenosine and SAH levels, it influences methylation reactions and chromatin structure, impacting gene expression programs in NB and other cancers." (PMID 41514864, 2025). "It was shown that in patients with cancer, the levels of adenosine in tumor cells are regulated primarily by ADK-mediated phosphorylation to AMP and not the effect of ADA." (PMID 35327609, 2022). "ADK expression is dysregulated in various cancer tissues, however, there has been no focused study on dissecting the roles of ADK isoforms in cancer cells." (PMID 31921385, 2019). "We observed different expression levels of ADK isoforms among these cancer cell lines as well as between non-cancer cell lines, such as MCF 10A and 184A1 (data not shown), which might be attributed to the heterogeneity of these cell lines." (PMID 31921385, 2019).
tumor (19 papers, 1978 to 2025). "Considering the changes that occur in the expression of ADK in the tumor tissue, it can be suggested that ADK is a potential diagnostic marker and a perspective target for anti-tumor therapy." (PMID 35327609, 2022). "Besides, a recent study on the epigenetic role of ADK-L on tumor cell lines revealed a direct association between the expression of ADK and DNA methylation." (PMID 35327609, 2022). "Other evidence of possible ADK involvement in tumordevelopment includes the relationship between ADK and angiogenic activity andcellular proliferation during ontogenesis, as well as the changes in ADKexpression in tumor tissue and its association with epigenetic regulation." (PMID 37538807, 2023). "Analysis initiated by fusions in the COSMIC-enriched cluster highlighted several putative or less appreciated oncogenic fusions, including CCAT1::CASC8 and VCL::ADK, based on their feature similarity to other well-known tumor-enriched fusions." (PMID 37323575, 2023). "We considered only SCC, as it was the tumor histotype that had an anomalous signaling of S1P compared to ADK." (PMID 37446018, 2023). "According to the published data, tumortissue shows a local increase in ADK activation, possibly due to adenosineaccumulation in the tumor microenvironment and its active metabolism." (PMID 37538807, 2023). "Wecurrently lack a clear understanding of the role of ADK in tumor development.Earlier papers show increased ADK gene expression levels and enzymatic activity in tumor tissue of CRC patients comparedto healthy tissue." (PMID 37538807, 2023). "This also provides a new direction for the treatment of tumors–targeting overexpression of ADK to regulate onsite adenosine level and DNA methylation, thereby affecting the proliferation and apoptosis of tumor cells." (PMID 35721189, 2022). "Patients with glioma also showed enhanced expression of the gene and protein of ADK in both the nucleus and cytoplasm of tumor cells." (PMID 35327609, 2022). "A lower SOS production was associated with a poor SCC prognosis (p < 0.05) and as compared to ADK (p < 0.04) and a low FEV 1, underlining a different evolutive pathway for each type of tumor." (PMID 28933405, 2016). "PDGFRα was significantly overexpressed in ADK compared to normal mucosa which may suggest its potential role in the development or the sustain of tumor cells." (PMID 33213472, 2020). "The results showed that the expression levels of ADK, ADSL, ATIC, DPYS, ENTPD2, TXNRD1, and UCK2 in at least one tumor cell line were consistent with the predictions." (PMID 37999212, 2023). "Most recently, an adenosine metabolic clearance enzyme, adenosine kinase (ADK), has been shown to influence methylation on tumor suppressor genes and tumor development and progression." (PMID 35721189, 2022). "It focuses on enzymes involved in the metabolism of adenosine-ADK and ADA and provides an overview of biological significance of ADK and ADA and their role in the development of tumor." (PMID 35327609, 2022). "Additionally, we identified an adenosine kinase (ADK) inhibitor, 5′-iodotubercidin (5′-IT) potentially inhibits INSM1 expression and NB tumor growth." (PMID 41514864, 2025). "Knockdown of ADK decreases the methylation level of the VEGFR2 promoter region, which elevates intracellular adenosine and promotes proliferation, migration, and angiogenesis of human endothelial cells —all aspects that may promote tumor growth." (PMID 35721189, 2022). "Thus, the application of ADK and ADA can become a perspective approach to anti-tumor therapy." (PMID 35327609, 2022).
infection (7 papers, 2007 to 2023). The state of being infected such as from the introduction of a foreign agent such as serum, vaccine, antigenic substance or organism. "Host nucleotide metabolism was transcriptionally activated during infection, and key enzymes in T. gondii salvage pathways including adenosine kinase (AK) and hypoxanthine phosphoribosyltransferase (HXGPRT) were highly expressed." (PMID 32255806, 2020). "In support of the idea that ADK is a component of the stress response, ADK activity has been observed to increase following infection of N. benthamiana plants with DNA and RNA viruses." (PMID 24498147, 2014). "Two parasite enzymes which are essential to nucleotide salvage, hypoxanthine-guanine phosphoribosyl transferase and adenosine kinase, were consistently expressed throughout infection, as was T. gondii PRS1 which creates the PRPP needed for nucleotide synthesis and salvage." (PMID 32255806, 2020).
neurodegenerative disease (3 papers, 2021 to 2022). A disorder of the central nervous system characterized by gradual and progressive loss of neural tissue and neurologic function. "Similarly, ADA and ADK have also been implicated in neurodegenerative diseases." (PMID 34635103, 2021). "Other enzymes involved in adenosine metabolism (ADA, ADK, CD39 and CD73) are also abnormally affected in AD, similar to other neurodegenerative diseases." (PMID 34635103, 2021).
cardiovascular disease (2 papers, 2023 to 2024). "Our primary focus is on their roles in cardiovascular diseases, the result uncovered involvement of ADK, BLVRA, ALDH1B1, UGDH, and HIBCH." (PMID 39369254, 2024).
hematological tumors (1 paper, 2025). "Our findings indicate that certain plasma proteins exhibit causative roles in various hematological tumors, specifically ISOC1 in 14 tumors, ADK in 11 tumors, FKBPL in 10 tumors, and BCL2 in 9 tumors." (PMID 41048997, 2025).
ADK also shares sentences with these, for which no sentence is quoted: Alzheimer disease (2 papers); Huntington disease (2); neurological diseases (2); adenocarcinoma (1); amyotrophic lateral sclerosis (1); Anxiety (1); Arthritis (1); brain hemorrhage (1); Cerebral ischemia (1); cholestasis (1); chronic obstructive pulmonary disease (1); Cirrhosis (1); developmental delay (1); diabetic retinopathy (1); dissociative amnesia (1); fibrosis (1); Focal cortical dysplasia (1); Granuloma (1); heart diseases (1); Hyperglycemia (1); ischemia (1); kidney tumours (1); liver dysfunction (1); mantle cell lymphoma (1); metabolic disease (1); metabolic syndrome (1); myeloma (1); Neurodevelopmental delay (1); neurodevelopmental disorder (1); neuropathic pain (1).
A further 10 diseases each share a sentence with ADK in 1 paper.